B4GALT1 (beta-1,4-galactosyltransferase 1)
Description:
Galactosyltransferase acting in the Golgi stacks. Catalyzes the transfer of galactose (Gal) from UDP-alpha-D-galactose in beta(1->4) linkage to the non-reducing terminal N-acetylglucosamine (GlcNAc) moieties of glycolipids and complex-type N-linked glycans. Adds one Gal residue to both GlcNAc beta(1->2)-linked to the alpha(1->3) and alpha(1->6) mannose antennae of complex-type N-glycans, enabling the formation of mono- and di-galactosylated glycoforms. Galactosylates complex-type N-glycans attached on the fragment crystallizable (Fc) of immunoglobulin-gamma isotypes (IgGs), a prerequisite for antibody glycan sialylation and related anti-inflammatory effector functions. Can also transfer a Gal residue to free GlcNAc to form N-acetyllactosamine. With LALBA/alpha-lactalbumin forms the lactose synthase complex responsible for production of large amounts of lactose in the lactating mammary gland. Interaction with LALBA alters the sugar substrate specificity of the catalytic domain, enabling high affinity binding of glucose and its transformation to lactose. [Isoform Long]: The cell surface form functions as a recognition molecule during a variety of cell to cell and cell to matrix interactions, like those occurring during development and egg fertilization, by binding to specific oligosaccharide ligands on opposing cells or in the extracellular matrix. Acts as a sperm receptor for ZP3 O-linked glycans on the zona pellucida leading to activation of G protein signaling and acrosome reaction. [Processed beta-1,4-galactosyltransferase 1]: The secreted form is proficient in galactosyltransferase activity and could be involved in glycan remodeling in biological fluids.
Synonyms: Beta4Gal-T1; b4Gal-T1; GGTB2; CDG2D; CLDLFIB; GT1; GTB
Tractability: Small molecule: a structure with a bound ligand is known; a high-quality ligand is known; it has a binding pocket of medium quality. Antibody: UniProt places it where antibodies can reach, with high confidence; its Gene Ontology location is reachable by antibodies, with high confidence; UniProt predicts a signal peptide or a membrane-spanning region. PROTAC: its protein half-life has been measured; a small molecule that binds it is known.
Target class: Enzyme
Gene: Protein-coding gene on chromosome 9 (33,100,493 to 33,167,359, reverse strand). Ensembl gene ENSG00000086062.
Subcellular location: Golgi apparatus, Golgi stack membrane; Golgi apparatus, Golgi stack membrane (Isoform Long); Cell membrane; Cell surface; Cell projection, filopodium; Golgi apparatus, Golgi stack membrane (Isoform Short); Secreted (Processed beta-1,4-galactosyltransferase 1)
Subcellular location (Human Protein Atlas): Golgi apparatus
Pathways (Reactome):
Disease: Defective B4GALT1 causes B4GALT1-CDG (CDG-2d); Defective B4GALT1 causes CDG-2d
Metabolism: Keratan sulfate biosynthesis; Lactose synthesis
Immune System: Neutrophil degranulation
Metabolism of proteins: N-Glycan antennae elongation
Reproduction: Interaction With Cumulus Cells And The Zona Pellucida
Signal Transduction: Pre-NOTCH Processing in Golgi
Gene Ontology:
Molecular function: beta-N-acetylglucosaminylglycopeptide beta-1,4-galactosyltransferase activity; lactose synthase activity; manganese ion binding; N-acetyllactosamine synthase activity; UDP-galactosyltransferase activity; galactosyltransferase activity; glycosyltransferase activity
Biological process: lipid metabolic process; oligosaccharide biosynthetic process; positive regulation of circulating fibrinogen levels; protein N-linked glycosylation; lactose biosynthetic process; carbohydrate metabolic process
Cellular component: basolateral plasma membrane; brush border membrane; cell surface; desmosome; external side of plasma membrane; extracellular exosome; extracellular region; Golgi apparatus; Golgi trans cisterna; membrane; plasma membrane; azurophil granule membrane; Golgi membrane; secretory granule membrane; filopodium; Golgi cisterna membrane; protein-containing complex
Genetic constraint (gnomAD): Loss-of-function variants: 16 observed, 32.87 expected, observed/expected ratio (o/e) 0.49, 90% interval 0.33 to 0.74. The upper end of that interval is the gene's LOEUF score, 0.74, which puts it in group 3 of 6, group 1 being the genes least tolerant of losing a copy. Missense variants: 445 observed, 500.02 expected, observed/expected ratio (o/e) 0.89, 90% interval 0.82 to 0.96. Synonymous variants: 221 observed, 200.78 expected, observed/expected ratio (o/e) 1.1, 90% interval 0.99 to 1.23.
Homologues: Orthologues: chimpanzee B4GALT1 (99% identical), macaque B4GALT1 (95% identical), rat B4galt1 (88% identical), pig B4GALT1 (87% identical), mouse B4galt1 (87% identical), dog B4GALT1 (83% identical), guinea pig B4GALT1 (66% identical), tropical clawed frog b4galt1.2 (56% identical), tropical clawed frog b4galt1 (54% identical), zebrafish b4galt1l (52% identical), zebrafish b4galt1 (39% identical), Caenorhabditis elegans bre-4 (33% identical), and 1 more. Paralogues in human: B4GALT2 (49% identical), B4GALT3 (42% identical), B4GALT4 (36% identical), B4GALT5 (34% identical), B4GALT6 (32% identical), B4GALT7 (24% identical).
Diseases named in the same sentence as B4GALT1 in open-access papers:
B4GALT1 is named in the same sentence as 66 diseases in open-access papers, as found by Europe PMC text mining. Sharing a sentence is not in itself a finding about the gene and the disease. The quoted sentences say what the papers report.
lung adenocarcinoma (11 papers, 2019 to 2025). A carcinoma that arises from the lung and is characterized by the presence of malignant glandular epithelial cells. "For instance, B4GALT1 has been shown to enhances N-linked glycosylation of PD-L1, thereby stabilizing PD-L1 and promoting immune evasion in lung adenocarcinoma, suggesting similar glycan-mediated immunomodulation in adenomyosis." (PMID 41356013, 2025). "In lung adenocarcinoma, β‐1,4‐galactosyltransferase 1 (B4GALT1) has been recognized as a direct catalyst of N‐linked glycosylation of PD‐L1, reinforcing its stability." (PMID 41322030, 2025). "Recent preclinical work supports combining B4GALT1 inhibition with immunotherapy: in a lung adenocarcinoma model, genetic or pharmacological inhibition of B4GALT1 enhanced CD8+ T-cell infiltration and synergized with anti–PD-1 therapy." (PMID 40860122, 2025). "B4GALT1 mediated galactosylation promotes immune escape in lung adenocarcinoma by up-regulating PD-L1 expression and inhibiting CD8+ T cell infiltration.Here, we found that elevated bisecting GlcNAc levels in BC cells promoted PD-L1 degradation." (PMID 40760673, 2025). "Another enzyme, Beta-1,4-Galactosyltransferase 1 (B4GALT1), has been implicated in the maintenance of the stemness in lung adenocarcinoma (LUAD) and CRC." (PMID 37760606, 2023). "In a variety of cancers, the B4GALTs family is associated with cancer cell proliferation, invasion, metastasis, and drug resistance.B4GALT1 is highly expressed in patients with lung adenocarcinoma (Zhang, Zhang & Yu, 2019)." (PMID 35111402, 2022). "On the one hand, B4GALT1 serves as an oncogene in clear cell renal cell carcinoma, muscle‐invasive bladder cancer, lung adenocarcinoma, breast cancer and leukaemia." (PMID 32902124, 2020). "With the increasing risk score of patients with lymph node metastasis of lung adenocarcinoma, the expression of high-risk mRNAs (HMMR, B4GALT1, ANGPTL4, EXT1, GPC1, RBCK1, SOD1, AGRN) was obviously upregulated." (PMID 31847905, 2019). "In a lung adenocarcinoma model, B4GALT1 knockdown enhanced CD8+ T cell infiltration and sensitized tumors to anti-PD-1 therapy, suggesting that 1105486 may have additional benefits in combination with immunotherapy." (PMID 40860122, 2025). "Moreover, the GSE166720 dataset, which classified 53 early-stage lung adenocarcinomas into indolent (AIS and MIA) and invasive tumours (IAC) according to pathological grade, showed that B4GALT1 mRNA expressions were higher in invasive tumours than in indolent tumours." (PMID 37303063, 2023).
leukemia (10 papers, 2016 to 2025). A malignant (clonal) hematologic disorder, involving hematopoietic stem cells and characterized by the presence of primitive or atypical myeloid or lymphoid cells in the bone marrow and the blood. "In addition, we found that B4GALT1 was significantly elevated in patients with non-M3 leukemia and cytogenetic risk (intermediate/poor)." (PMID 36568388, 2022). "For example, cells carrying mutations exclusively in JAK2 specifically upregulated B4GALT1, which is associated with acquisition of drug resistance in leukemia, and cells with mutations in epigenetic modifiers specifically upregulated PITX1, which has been previously implicated in leukemogenesis." (PMID 30765193, 2019). "Notably, B4GALT1 protein has been previously associated with multi-drug-resistant cell phenotype in human leukemia and other haematological malignancies." (PMID 31717588, 2019). "B4GALT1 encoding β-1, 4-Galactosyltransferase is also frequently co-amplified and overexpressed, and has been demonstrated to mediate multidrug resistance in leukemia cell lines." (PMID 29212506, 2017). "In multidrug resistance leukemia patients, highly expressed B4GALT1 regulated the hedgehog pathway, and were associated with the expression of p-glycoprotein and multidrug resistance-associated protein, resulting in the specific drug-resistant phenotypes of leukemia cell lines." (PMID 27516205, 2016). "Recent study demonstrated that B4GALT1 gene family play an important role in the resistance of human leukemia cells to therapeutic drugs." (PMID 27516205, 2016). "Given B4GALT1’s role in leukemia and lung cancer, 1105486 or its analogs may have broader applications." (PMID 40860122, 2025).
lung carcinoma (9 papers, 2009 to 2025). "We also found that breast, gastric, liver, and lung cancer cell lines expressed both galectin-8 and B4GALT1." (PMID 39231945, 2024). "Collectively, these data validated the physiological relevance of IGFBP5 and B4GALT1 as specific secreted protein markers for ASCL1High NE-lung cancers." (PMID 31324758, 2019). "Remarkably, 84% of cancer types exhibit upregulation of B4GALT1 expression compared to healthy tissues, including both lung cancers LUAD and LUSC." (PMID 31717588, 2019). "The increased expression of B4GALT1 led to the formation of the sialyl-Lewis X determinant, which correlated with metastatic potentials of human lung cancer cells and U937 cells." (PMID 27092876, 2016). "Furthermore, B4GALT1 led to the formation of the sialyl-Lewis X determinant, which was used as a tumor marker for lung cancer, but is also expressed by pulmonary epithelial cell in patients with IPF." (PMID 36499368, 2022). "Furthermore, in order to assess the role of B4GALT1 in the generation of 3D spheroids we transfected a B4GALT1 siRNA in NCI–H460 lung cancer cells." (PMID 31717588, 2019). "Since our lab's former work on B4GALTs in lung cancer, liver cancer and glioma suggested its vital role in cancers, we analyzed B4GALT1 expression by IHC in ccRCC clinical specimens and its association with clinicopathological characteristics and clinical outcome." (PMID 27092876, 2016). "Of these 64 mRNAs, 38 mRNAs were down-regulated in lung cancer patients, of which the top 5 mRNAs were CHGB, B4GALT1, ZNF434, GLB1, and ASCL1 (p≤0.0001)." (PMID 25705890, 2015). "The role of cell surface B4GALT1 in human cancer has been reported; it is an estrogen-regulated gene in MCF-7 cells, and its level was altered in highly metastatic lung cancer cells compared with its less metastatic parental cells." (PMID 19662090, 2009). "The B4GALT1 promoter is more heavily methylated in invasive CRC lesions than in non-invasive CRC lesions, and B4GALT1 expression has been suggested as a prognostic biomarker in renal, bladder, and lung cancer." (PMID 39231945, 2024). "Since some studies suggested a possible association between UIP/IPF and lung cancer, we asked whether B4GALT1 expression was also expressed in human lung tissues from a patient with both UIP/IPF and lung cancer." (PMID 36499368, 2022). "However, the expression of B4GALT1 in IPF tissue and cell lines, as well as in UIP/IPF associated with lung cancer, was never tested before." (PMID 36499368, 2022).
breast carcinoma (8 papers, 2017 to 2024). "The expression of B4GALT1 has been known to quickly respond to estrogen treatment, and the ERα-dependent activation of cell proliferation through membrane B4GALT1 implicated its crucial role in breast cancer development." (PMID 35976950, 2022). "Conversely, in breast cancer, estrogen-induced expression of B4GALT1 is associated with enhanced breast cancer cell proliferation, and thus estrogen receptor agonists have been suggested as a potential therapeutic approach." (PMID 28672878, 2017). "RBMS1 directly stabilizes the mRNA of B4GALT1, a glycosyltransferase that promotes PD-L1 maturation and stabilization via mediating the glycosylation of PD-L1 in breast cancer." (PMID 37628671, 2023). "Meanwhile, depletion of B4GALT1 in breast cancer cells with overexpression of RBMS1 notably reduced the glycosylation of PD-L1." (PMID 35538152, 2022). "We further re-expressed B4GALT1 in RBMS1-depleted breast cancer cells, and found that re-expression of B4GALT1 rescued RBMS1 depletion-induced decrease of PD-L1 glycosylation." (PMID 35538152, 2022). "We subsequently analyzed the clinical correlation of RBMS1 and B4GALT1 in TCGA breast cancer dataset, and found that the expression level of B4GALT1 is positively correlated to the level of RBMS1, especially in TNBC dataset." (PMID 35538152, 2022). "We found that the glycosyltransferase beta-1,4-galactosyltransferase 1 (B4GALT1) was one of the top hits whose expression level was significantly decreased upon RBMS1 depletion in breast cancer cells." (PMID 35538152, 2022). "Knock-down of the B4GALT1 gene and the inhibition of its function has been shown to inhibit the estrogen-induced proliferation of breast cancer cell lines." (PMID 33892787, 2021). "SCUBE2, B4GALT1 and MYO3B genes also exemplify the relationship between decitabine-induced gain of multiple ER-bound enhancer–promoter interactions and activation of their ER target genes that are associated with good prognosis in ER+ breast cancer." (PMID 38182927, 2024). "Knockdown of B4GALT1 could indeed reduce PD-L1 glycosylation in multiple breast cancer cells in the absence or presence of IFN-γ, whereas overexpression of B4GALT1 elevated the glycosylation of PD-L1." (PMID 35538152, 2022).
colorectal cancer (6 papers, 2009 to 2024). A primary or metastatic malignant neoplasm that affects the colon or rectum. "This study aims to investigate the diagnostic, prognostic, and therapy-response predictive value of the glyco-gene B4GALT1 in colorectal cancer (CRC) patients." (PMID 31635093, 2019). "It would be interesting to know how many wild type K-ras colorectal cancers harbor B4GALT1 methylation as a mechanism of EGFR resistance." (PMID 19662090, 2009). "To address this aspect, we performed colocalization experiments of the enzymes involved in our predicted reactions, namely B4GalT1, MGAT3, and ST6Gal1, in kidney COS-7 cells and CaCo-2 colorectal cancer cells." (PMID 29133956, 2017). "In this study, we identified PAPSS2, TUBG2, NTRK2, B4GALT1 and OSMR as genes harboring cancer-specific promoter methylation in human colorectal cancer." (PMID 19662090, 2009).
pancreatic ductal adenocarcinoma (5 papers, 2021 to 2025). An infiltrating adenocarcinoma that arises from the epithelial cells of the pancreas. "For instance, B4GALT1 expression has been shown to be associated with a worse prognosis in bladder cancer, clear cell renal cell carcinomas, and pancreatic ductal adenocarcinomas." (PMID 37303063, 2023). "PANC-1 cells, a widely used model for pancreatic ductal adenocarcinoma (PDAC) that exhibits high expression of B4GALT1, were chosen to evaluate the anticancer potential of compound 1105486." (PMID 40860122, 2025). "Targeting aberrant β-1,4-galactosyltransferase 1 (B4GALT1) activity represents an unexplored therapeutic avenue for pancreatic ductal adenocarcinoma (PDAC)." (PMID 40860122, 2025). "In previous studies, B4GALT1 expression predicted prognosis in pancreatic ductal adenocarcinomas and bladder cancer." (PMID 37303063, 2023). "B4GALT1 upregulates glycosylation of CDK11p110 and therefore confers chemoresistance of pancreatic ductal adenocarcinomas." (PMID 34745942, 2021). "Finally, experiments performed in an orthotopic and heterotopic pancreatic ductal adenocarcinoma (PDAC) model, demonstrated that B4GALT1 belongs to a new signaling pathway, including p65 upstream and CDK11p110 downstream, respectively, involved in chemoresistance of pancreatic cancer." (PMID 36499368, 2022).
bladder cancer (4 papers, 2018 to 2023). "We aimed to establish the expression of B4GALT1 in bladder cancer and its connection to patient outcomes, as well as forecasting the advantages of adjuvant chemotherapy (ACT) in patients with muscle-invasive bladder cancer (MIBC)." (PMID 29793447, 2018). "Most significantly, the advantage of ACT noted in pT3/4 or N+ bladder cancer patients with low B4GALT1 expression was greater than in patients with a high B4GALT1 expression." (PMID 29793447, 2018). "To explore the underlying mechanisms of low B4GALT1 expression patients benefit from ACT, we figured that the efficient immune cells have a pivotal part in the reaction of bladder cancer to chemotherapy, which is supported by a recent study." (PMID 29793447, 2018). "For instance, low expressions of glycosyltransferase genes B4GALT1, EXT1, MGAT5B and POFUT1 predicted poor patient’s survival in bladder cancer." (PMID 36110252, 2022). "To examine the mechanism of low B4GALT1 expression that provides patients with advantages from ACT, we considered that the immune system, in particular the efficient immune cells, has a crucial part in the reaction of bladder cancer to chemotherapy." (PMID 29793447, 2018).
glioblastoma (4 papers, 2022 to 2024). The most malignant astrocytic tumor (WHO grade IV). "High B4GALT1 expression was associated with disease-free survival of patients with glioblastoma, and B4GALT1 knockdown increased apoptosis and autophagy." (PMID 37907465, 2023). "Conversely, B4GALT1 knockdown in mice resulted in an inhibition of glioblastoma development and increased survival." (PMID 37188790, 2023). "Moreover, B4GALT1 knockdown was responsible for an increase in apoptosis and autophagy of glioblastoma both in vitro and in vivo." (PMID 36499368, 2022). "Among them, B4galt1 may be able to regulate apoptosis and autophagy of glioblastoma." (PMID 39233353, 2024).
hepatocellular carcinoma (4 papers, 2018 to 2023). A malignant tumor that arises from hepatocytes. "The results indicated that B4GALT1 is expressed in all major cell types, including hepatocellular carcinoma (HCC), myeloid, T, NK, B, plasma, endothelial, and fibroblast cells at variable levels." (PMID 37907465, 2023). "Here, we found that B4GALT1 was significantly downregulated in hepatocellular carcinoma (HCC) tissue compared with the adjacent liver tissue, and low B4GALT1 expression was associated with vascular invasion and poor overall survival in patients with HCC." (PMID 37907465, 2023). "Furthermore, B4GALT1 interacts directly with EGFR inhibiting the dimerization of the receptor and the tyrosine phosphorylation and its activation in human hepatocellular carcinoma cells, suggesting an inhibitory role of B4GALT1 in EGFR signaling pathway." (PMID 31635093, 2019). "A previous study showed that B4GALT1 was upregulated in HCC, and plays a positive role in HBx-induced hepatoma cell growth depending on its glycosylation activity." (PMID 37907465, 2023). "Interestingly, previous works have shown that the ectopic expression of cell surface B4GALT1 promotes apoptosis in human hepatocellular carcinoma cells inhibiting EGFR dimerization and tyrosine phosphorylation, indicating that B4GALT1 may be an inhibitor of EGFR signaling." (PMID 31635093, 2019).